ACTL9 (actin like 9)
Description:
Testis-specic protein that plays an important role in fusion of proacrosomal vesicles and perinuclear theca formation.
Synonyms: HSD21; MGC33407; SPGF53
Tractability: No criterion of Open Targets' tractability assessment is met for any kind of drug.
Gene: Protein-coding gene on chromosome 19 (8,697,400 to 8,698,795, reverse strand). Ensembl gene ENSG00000181786.
Subcellular location: Cytoplasmic vesicle, secretory vesicle, acrosome; Cytoplasm, cytoskeleton, perinuclear theca
Subcellular location (Human Protein Atlas): Acrosome; Equatorial segment
Gene Ontology:
Molecular function: protein binding; structural constituent of cytoskeleton
Biological process: acrosome assembly; fertilization; cytoskeleton organization
Cellular component: acrosomal vesicle; perinuclear theca; sperm head; actin cytoskeleton
Genetic constraint (gnomAD): Loss-of-function variants: 2 observed, 3.69 expected, observed/expected ratio (o/e) 0.54, 90% interval 0.22 to 1.58. That is too few expected variants to judge how well the gene tolerates losing a copy. Missense variants: 597 observed, 561.27 expected, observed/expected ratio (o/e) 1.06, 90% interval 0.99 to 1.14. Synonymous variants: 283 observed, 267.57 expected, observed/expected ratio (o/e) 1.06, 90% interval 0.96 to 1.17.
Homologues: Orthologues: chimpanzee ACTL9 (99% identical), macaque ACTL9 (95% identical), pig ACTL9 (82% identical), rabbit ACTL9 (82% identical), dog ACTL9 (81% identical), mouse Actl9 (77% identical), rat Actl9 (75% identical), rat Actl9b (63% identical), guinea pig ACTL9 (62% identical). Paralogues in human: ACTL7A (40% identical), ACTL7B (38% identical), ACTB (37% identical), ACTG1 (37% identical), ACTA2 (36% identical), ACTC1 (36% identical), ACTG2 (36% identical), ACTA1 (36% identical), ACTBL2 (35% identical), ACTRT2 (35% identical), ACTR1B (32% identical), ACTR1A (32% identical), and 14 more.
Diseases named in the same sentence as ACTL9 in open-access papers:
ACTL9 is named in the same sentence as 6 diseases in open-access papers, as found by Europe PMC text mining. Sharing a sentence is not in itself a finding about the gene and the disease. The quoted sentences say what the papers report.
male infertility (2 papers, 2023 to 2025). The inability of the male to effect fertilization of an ovum after a specified period of unprotected intercourse. "Most recently, the depicted phenotype of peeling acrosomes has been described in humans where coding point mutations in the actin-like 7A (ACTL7A) and ACTL7C (aka ACTL9) genes have been identified as pathogenic variants of significance in cases of complete human male infertility." (PMID 36734600, 2023). "ACTL9 (actin like 9) is associated with spermatogenic failure 53 and non-syndromic male infertility." (PMID 40428427, 2025).
colon cancer (1 paper, 2012). "A comparison of the our aCGH data with a list of 68 genes identified through the sequencing of 11 colon cancer tumors revealed that all of these genes, except ACTL9, are altered in at least one of the 30 tumors analyzed here." (PMID 22879877, 2012).
eczema (1 paper, 2017). "This study identified three new genes (OVOL1, ACTL9, KIF3A) that are associated with eczema." (PMID 30402607, 2017).
Infertility (1 paper, 2025). "Later studies revealed other genetic causes of sperm-related human infertility, including homozygous pathogenic variants in the actin-like 9 (ACTL9) gene, disruption of the IQ motif-containing N (IQCN) gene, and bi-allelic mutations in PLCZ1 (the gene coding for PLCζ in humans)." (PMID 40649994, 2025).
ACTL9 also shares sentences with these, for which no sentence is quoted: itch (1 paper); spermatogenic failure (1).